GABBR1 (gamma-aminobutyric acid type B receptor subunit 1)
Description:
Component of a heterodimeric G protein-coupled receptor for GABA, formed by GABBR1 and GABBR2. Within the heterodimeric GABA receptor, only GABBR1 seems to bind agonists, while GABBR2 mediates coupling to G proteins. Ligand binding causes a conformation change that triggers signaling via guanine nucleotide-binding proteins (G proteins) and modulates the activity of down-stream effectors, such as adenylate cyclase. Signaling inhibits adenylate cyclase, stimulates phospholipase A2, activates potassium channels, inactivates voltage-dependent calcium-channels and modulates inositol phospholipid hydrolysis. Calcium is required for high affinity binding to GABA (By similarity). Plays a critical role in the fine-tuning of inhibitory synaptic transmission. Pre-synaptic GABA receptor inhibits neurotransmitter release by down-regulating high-voltage activated calcium channels, whereas postsynaptic GABA receptor decreases neuronal excitability by activating a prominent inwardly rectifying potassium (Kir) conductance that underlies the late inhibitory postsynaptic potentials. Not only implicated in synaptic inhibition but also in hippocampal long-term potentiation, slow wave sleep, muscle relaxation and antinociception (Probable). Activated by (-)-baclofen, cgp27492 and blocked by phaclofen. Isoform 1E may regulate the formation of functional GABBR1/GABBR2 heterodimers by competing for GABBR2 binding. This could explain the observation that certain small molecule ligands exhibit differential affinity for central versus peripheral sites.
Synonyms: GABABR1; Gb1; GPRC3A; hGB1a; GABBR1-3; NEDLC
Tractability: Small molecule: an approved drug acts on it; a structure with a bound ligand is known; a high-quality ligand is known; it belongs to a druggable protein family. Antibody: UniProt places it where antibodies can reach, with high confidence; its Gene Ontology location is reachable by antibodies, with high confidence; UniProt predicts a signal peptide or a membrane-spanning region. PROTAC: ubiquitination databases record sites on it; its protein half-life has been measured; a small molecule that binds it is known.
Target class: Small molecule receptor (family C GPCR); GABA-B receptor; Membrane receptor; Neurotransmitter receptor (family C GPCR); Family C G protein-coupled receptor
Gene: Protein-coding gene on chromosome 6 (29,555,629 to 29,633,976, reverse strand). Ensembl gene ENSG00000204681.
Subcellular location: Cell membrane; Postsynaptic cell membrane; Cell projection, dendrite; Secreted (Isoform 1E)
Subcellular location (Human Protein Atlas): Plasma membrane; Vesicles; Basal body; Primary cilium tip
Pathways (Reactome):
Neuronal System: Activation of G protein gated Potassium channels; GABA B receptor activation; Inhibition of voltage gated Ca2+ channels via Gbeta/gamma subunits
Signal Transduction: Class C/3 (Metabotropic glutamate/pheromone receptors); G alpha (i) signalling events
Gene Ontology:
Molecular function: G protein-coupled GABA receptor activity; protein binding; extracellular matrix protein binding; G protein-coupled neurotransmitter receptor activity; G protein-coupled receptor activity; GABA receptor activity; protein heterodimerization activity
Biological process: adenylate cyclase-inhibiting G protein-coupled receptor signaling pathway; gamma-aminobutyric acid signaling pathway; neuron-glial cell signaling; synaptic transmission, GABAergic; G protein-coupled receptor signaling pathway; negative regulation of cell population proliferation; negative regulation of dopamine secretion; negative regulation of epinephrine secretion; negative regulation of gamma-aminobutyric acid secretion; negative regulation of synaptic transmission; osteoblast differentiation; positive regulation of glutamate secretion; positive regulation of growth hormone secretion; regulation of glutamate secretion; response to ethanol; response to nicotine
Cellular component: G protein-coupled GABA receptor complex; G protein-coupled receptor heterodimeric complex; plasma membrane; postsynaptic membrane; axolemma; cytoplasm; dendrite; dendritic shaft; dendritic spine; endoplasmic reticulum membrane; extracellular region; G protein-coupled receptor dimeric complex; GABA receptor complex; GABA-ergic synapse; glutamatergic synapse; membrane; mitochondrial membrane; neuronal cell body; presynapse; presynaptic membrane; Schaffer collateral - CA1 synapse; synaptic membrane; synaptic vesicle
Genetic constraint (gnomAD): Loss-of-function variants: 31 observed, 110.61 expected, observed/expected ratio (o/e) 0.28, 90% interval 0.21 to 0.38. The upper end of that interval is the gene's LOEUF score, 0.38, which puts it in group 1 of 6, group 1 being the genes least tolerant of losing a copy. Missense variants: 703 observed, 1,236 expected, observed/expected ratio (o/e) 0.57, 90% interval 0.53 to 0.61. Synonymous variants: 441 observed, 485.29 expected, observed/expected ratio (o/e) 0.91, 90% interval 0.84 to 0.98.
Homologues: Orthologues: macaque GABBR1 (99% identical), pig GABBR1 (99% identical), chimpanzee GABBR1 (99% identical), mouse Gabbr1 (99% identical), rat Gabbr1 (99% identical), dog GABBR1 (98% identical), rabbit GABBR1 (97% identical), guinea pig GABBR1 (83% identical), tropical clawed frog gabbr1 (79% identical), zebrafish gabbr1a (73% identical), zebrafish gabbr1b (72% identical), Drosophila melanogaster GABA-B-R1 (41% identical), and 1 more. Paralogues in human: GABBR2 (30% identical), GPR156 (11% identical).
Diseases named in the same sentence as GABBR1 in open-access papers:
GABBR1 is named in the same sentence as 133 diseases in open-access papers, as found by Europe PMC text mining. Sharing a sentence is not in itself a finding about the gene and the disease. The quoted sentences say what the papers report.
schizophrenia (28 papers, 2008 to 2025). A major psychotic disorder characterized by abnormalities in the perception or expression of reality. "Dysfunction of GABBR1 has been implicated in the pathogenesis of neurological disorders such as schizophrenia and epilepsy." (PMID 41301871, 2025). "DNA methylation of the GABBR1 gene has further been implicated in obsessive-compulsive disorder (OCD) as well as schizophrenia." (PMID 29026448, 2017). "GABBR1 is located in the 6p22 chromosomal region that has been implicated in schizophrenia for a long time." (PMID 23391219, 2013). "The GABBR1 gene was mapped to chromosome 6p21.31 within the HLA class I region that also contains susceptibility loci for multiple sclerosis, epilepsy, and schizophrenia." (PMID 21283797, 2011). "GABBR1, a neurotransmitter receptor, has been implicated in schizophrenia." (PMID 39765520, 2024). "In addition, we found that the top two microRNAs with the highest number of targets known to be associated with schizophrenia both regulate GABBR1, a feature shared only by 9 other differentially methylated genes listed in Genecards." (PMID 26450699, 2015). "Interestingly, the work is in line with a previous finding by the authors, also published in Biology Direct, where they also concluded that the downregulation of GABBR1 via an endogenous retroviral element might be the cause of schizophrenia." (PMID 26450699, 2015). "From this they conclude that GABBR1 might play a causative role in schizophrenia." (PMID 26450699, 2015). "In one study of schizophrenia, hypermethylation of a specific ERV-W LTR insertion located in the regulatory region of the GABBR1 gene was associated with risk of schizophrenia." (PMID 28439515, 2017). "A protein-protein interaction network, constructed from schizophrenia-related, differentially methylated genes, regulated by one of the top two microRNAs revealed that almost all of the interacting partners of GABBR1 were also hypermethylated." (PMID 26450699, 2015). "The analysis revealed that GABBR1 is regulated by both of the top two microRNAs and acts as a hub by interacting with many schizophrenia-related genes and sharing several types of transcription-binding sites with its interactors." (PMID 26450699, 2015). "The top two microRNAs both regulate GABBR1, from which they conclude again that this gene is of special interest in schizophrenia." (PMID 26450699, 2015). "Our finding of a full-length HERV-W LTR in the regulatory region of the GABA receptor B1 gene GABBR1 implicates it in a subset of cases of schizophrenia." (PMID 23391219, 2013). "We suggest GABBR1, GABA receptor B1 implicated in schizophrenia based on a HERV-W LTR in the regulatory region of GABBR1." (PMID 23391219, 2013). "GWAS of schizophrenia has identified a locus in the gene GABBR1 in East Asian population." (PMID 38503926, 2024). "Among the genes implicated in schizophrenia, susceptibility variants linked to genes affecting GABAergic transmission (GABA B receptor components GABBR1 and GABBR2, and loci linked to proteins that mediate GABA receptor turnover, such as ankyrin-G (ANK3)) were reported." (PMID 36979236, 2023). "In addition, the loci for both GABBR1 (6p21.3) and GABBR2 genes (5q34) have been recognized as the susceptibility loci for schizophrenia." (PMID 34067760, 2021). "Also, significant reductions in Gabbr1 and Gabbr2 gene expression were reported to be present in lateral cerebellum of subjects with schizophrenia, bipolar disorder, and major depression, providing further evidence of GABAergic dysfunction in these diseases." (PMID 33006978, 2020). "We hypothesized before that a long terminal repeat (LTR) of the endogenous retrovirus HERV-W in the cis regulatory region of GABBR1 might account for the downregulation of GABBR1 in schizophrenia." (PMID 26450699, 2015). "We find that GABBR1 has a central importance in schizophrenia, even if no direct cause and effect have been shown for it for the time." (PMID 26450699, 2015).
schizophrenia (continued). "As GABBR1 is regulated by both of the two most prevalent microRNAs, it has an even higher chance to be the major driver of the affected biochemical pathways in schizophrenia." (PMID 26450699, 2015). "Taken together, we find that GABBR1 has a central importance in schizophrenia, even if no direct cause and effect have been shown for it for the time." (PMID 26450699, 2015). "The author presents a new hypothesis about the role a GABA receptor, GABBR1 might play in the aetiology of schizophrenia." (PMID 23391219, 2013). "Furthermore, a subunit for GABA receptor 1B (GABBR1), DTW Domain Containing 2 (DTWD2), and DISC1-Binding Zinc-Finger Protein (ZNF365), have been associated with multiple often comorbid disorders, including addiction, bipolar disorder, and schizophrenia." (PMID 31040859, 2019). "In this paper we focused on the role GABA B1 receptor (GABBR1) might play in schizophrenia." (PMID 26450699, 2015). "Fatemi and coworkers detected significant reduction in GABBR1 and GABBR2 protein level in the lateral cerebella and superior frontal cortex from patients with schizophrenia, bipolar disorder, and major depression when compared to healthy controls." (PMID 34067760, 2021). "Parallel and multistep analysis in this research showed that SLC1A1, DRD2, DRD4, BDNF, ESR1, CDH2, GRIN2B, TNFa, GABBR1, and OLIG2 are common genes between schizophrenia and OCD which ESR1, DRD2, GABBR1, TNFa, and CDH2 are the most important individuals." (PMID 31086558, 2018). "Expression of GABAB receptor subunits 1 and 2 (GABBR1 and GABBR2) were reported to alter significantly in the lateral cerebellum of subjects with schizophrenia." (PMID 30341038, 2018). "Though one report showed a weak correlation between GABBR1 gene and schizophrenia, two other found no connection." (PMID 34067760, 2021). "Besides GABBR1, which had the strongest match with the LTR sequence of HERV-W, several other schizophrenia-related genes had a partial match." (PMID 23391219, 2013). "The protein-protein interaction map of genes regulated by one of the two top microRNAs shows that GABBR1 and AKT1 are both hub proteins, forming a plausible network of interacting proteins, comprising several key players in the GABA and signaling pathways in schizophrenia." (PMID 26450699, 2015).
epilepsy (19 papers, 2008 to 2025). A brain disorder characterized by episodes of abnormally increased neuronal discharge resulting in transient episodes of sensory or motor neurological dysfunction, or psychic dysfunction. "Among these, epilepsy is a frequent condition in individuals with GABBR1 and GABBR2 variants, consistent with the increased excitation–inhibition ratio and seizure susceptibility observed in GBR-deficient mice." (PMID 40756990, 2025). "Pathogenic variants in GABBR1 are commonly associated with a clinical phenotype that includes neurodevelopmental delay and/or epilepsy." (PMID 40756990, 2025). "Protein-protein interaction (PPI) analysis indicated that the protein encoded by KCNJ15 directly interacts with the two epilepsy drug targets encoded by GABBR1 and GABBR2, further supporting the role of KCNJ15 in epilepsy." (PMID 40342929, 2025). "Pathogenic variants in the GABBR1 and GABBR2 genes, which encode the GB1 and GB2 subunits of GABABRs, are implicated in several neurological and developmental disorders, including epilepsy and autism." (PMID 38076211, 2023). "As GABA represents the main neurotransmitter in the brain, GABBR1 and/or GABBR2 have been implicated in the pathogenesis of various neurological or psychiatric disorders such as epilepsy, Huntington’s disease, Alzheimer’s disease, autism, and depression." (PMID 37762034, 2023). "Qualitatively, the peptide overlap occurs in human proteins canonically associated with epilepsy such as gamma-aminobutyric acid receptor subunit alpha-1 (GBRA1), gamma-aminobutyric acid type B receptor subunit 1 (GABR1), sodium channel protein subunits (SCN1A, SCN2A." (PMID 24982805, 2014). "Patient P_000512 with short segment HSCR, epilepsy and intellectual disability, has a large de novo deletion (6p22.1—p21.33) which affects the ENS genes GABBR1, GNL1 and TUBB." (PMID 34358225, 2021).
Anxiety (9 papers, 2017 to 2024). Intense feelings of nervousness, tension, or panic often arise in response to interpersonal stresses. "Of interest for our study, polymorphism in DTWD2 has shown to interact with FKBP5 in trans and GABBR1 has been associated with DNA methylation changes in newborns following maternal anxiety during pregnancy." (PMID 31040859, 2019). "In conclusion, we showed that pregnancy anxiety is associated with fetal DNA methylation changes, identifying GABBR1 as one of the top candidate genes associated with pregnancy anxiety in male newborns." (PMID 29026448, 2017). "In conclusion, our results show that pregnancy anxiety is associated with differential DNA methylation patterns in newborns and that our candidate gene GABBR1 is associated with infant hypothalamic-pituitary-adrenal axis response to a stressor." (PMID 29026448, 2017). "However, as DNA methylation at several GABBR1 CpG units was associated with the pregnancy anxiety x gender interaction term (CpG_8 p = 0.045, CpG_9.10 p = 0.014, CpG_14.15 p = 0.029, and a trending effect at CpG_3 p = 0.06), data were stratified by gender." (PMID 29026448, 2017). "Elise Beau Vangeel demonstrated that pregnancy stress corresponds to fetal DNA methylation modifications, revealing GABBR1 as one of the best possible genes responsible for pregnancy anxiety in neonates." (PMID 39336733, 2024). "In the current study, we identified GABBR1 DNA methylation as affected by prenatal anxiety exposure in a birth cohort." (PMID 29026448, 2017). "None of the GABBR1 DMR CpG units were significantly associated with pregnancy anxiety in female newborns." (PMID 29026448, 2017). "We reproduced and expanded our earlier findings in an animal model of GABBR1, CCKBR, and DYNLL2 as top genes involved in anxiety." (PMID 36878964, 2023).
colorectal cancer (7 papers, 2016 to 2025). A primary or metastatic malignant neoplasm that affects the colon or rectum. "Inhibition of GABBR1 (gamma-amino-butyric acid type B receptor 1) has been associated with progression of colorectal cancer, whereas overexpression of this gene served as an inhibitor of miRNAs that would otherwise lead to proliferation of this cancer." (PMID 30962767, 2019). "In colorectal cancer, decreased GABBR1 fosters the proliferation and invasion; overexpression of GABBR1 has the opposite." (PMID 35140786, 2022). "We will perform further studies to investigate the downstream pathway of GABBR1 in colorectal cancer." (PMID 27230463, 2016). "This study uncovered the mechanism of proliferation and invasion regulation via this miRNAs family / GABBR1 signaling pathway and provided an insight into further therapeutic targets of colorectal cancer cells." (PMID 27230463, 2016). "In conclusion, miR‐106a/b, miR‐20a/b, and miR‐17 contribute to the proliferation and invasion of colorectal cancer by targeting their common target gene, GABBR1, and played a critical role in the proliferation and invasion of colorectal cancer." (PMID 27230463, 2016). "In summary, we uncovered that the miR‐106a/b, miR‐21a/b, miR‐17 which were higher expressed in the colorectal cancer tissues than in normal tissues downregulated the GABBR1 expression to influence the proliferation and invasion of colorectal cancer." (PMID 27230463, 2016). "Overexpression or activation of GABBR1 significantly inhibited the colorectal cancer cell, HCT116 cells proliferation." (PMID 27230463, 2016). "In our study, we found that miR‐106a/b, miR‐20a/b, and miR‐17 directly targeted the same site of the GABBR1 3′UTR in colorectal cancer." (PMID 27230463, 2016). "Our next unanswered question is how the pathway of miR‐106a/b, miR‐20a/b, and miR‐17 regulate GABBR1 to influence the colorectal cancer proliferation and invasion." (PMID 27230463, 2016). "Moreover, miR-20a promotes epithelial–mesenchymal transition by suppressing the expression of genes such as SMAD4 and GABBR1, thereby facilitating invasion in colorectal cancer." (PMID 40693022, 2025). "Additionally, we found that miR‐106a/b, miR‐20a/b, and miR‐17 targeted GABBR1 to regulate the GABB signaling during the colorectal cancer cells growth." (PMID 27230463, 2016). "Next, we hypothesized that GABBR1 was also involved in the proliferation and invasion of colorectal cancer cell." (PMID 27230463, 2016). "So, the agonist of GABBR1 signaling might be the potential effective drug for colorectal cancer therapy." (PMID 27230463, 2016).
depression (7 papers, 2017 to 2024). "Furthermore, we discovered other target genes and drug repurposing candidates for depression, the efficacies of which are supported by published evidence; for example, muromanab, which targets CD3D/CD247, and taurine, which targets GABBR1." (PMID 36009493, 2022).